ILK (integrin linked kinase)
Diseases named in the same sentence as ILK in open-access papers (continued):
Sharing a sentence is not in itself a finding about the gene and the disease.
cancer (continued). "A previous study has suggested that integrin-linked kinase overexpression downregulates MMP-9 during TGF-β2-induced EndMT, and elevated MMP-9 increases the invasive capacity of cancer cells." (PMID 32296578, 2020). "The ILK pathway was identified as the primary pathway that was enriched in cancer tissues compared to adjacent normal tissues." (PMID 33256002, 2020). "In the current study, the divergent cancer subtypes of ILC and IDC, which differ in regard to their EMT status, were studied as PDXs in order to examine the relationship between EMT, ITGA2/B1 and ILK in cancer progression, through serial passages in mice." (PMID 33276802, 2020). "Since ILK played crucial role in cancer cell motility, we evaluated the effect of cpd22 on cancer cell invasion and metastasis." (PMID 31897228, 2020). "Inhibition of ILK activity by Cpd22 treatment significantly reduced the viability of all cancer cell lines tested." (PMID 32260415, 2020). "Being part of mTORC2, Rictor was shown to regulate the ability of ILK to promote Akt phosphorylation and cancer cell survival, as depletion of ILK and Rictor from BC cells blocked Akt Ser473 phosphorylation and induced apoptosis." (PMID 33043811, 2020). "Activation of Smad 2/3, Snail1 and ILK was analyzed in the PMCs exposed to autologous and cancer-derived CM." (PMID 31086083, 2019). "In some cancers, however, ILK is often overexpressed, leading to the increased cancer growth with cell proliferation, migration, and epithelial-mesenchymal transition." (PMID 30636169, 2019). "In vitro, QLT-0267 shows a significant selectivity for cancer cells with supernumerary centrosomes, compared to normal cells, indicating that ILK inhibition provides a selective way of targeting cancer cells." (PMID 29757235, 2018). "ILK is a well-recognized cancer cell survival promoting protein, and its overexpression is associated with enhanced tumorigenicity." (PMID 30002625, 2018). "Other studies also suggest that the ILK/β-parvin/cofilin pathway mediates invasiveness and metastatic behavior of cancer cells." (PMID 29755929, 2018). "Although many studies have elucidated ILK and its role in various cancers, little is known about its role in the context of viral infections." (PMID 29085037, 2017). "Previous studies in cancer cells provided evidence that among other functions ILK is involved in cytoskeletal reorganization and cell survival, and its deregulation can contribute to errors in cell division and genomic instability." (PMID 28114363, 2017). "Inhibition of ILK has been shown to induce apoptosis and cell cycle arrest, making ILK an attractive therapeutic target for cancer treatment." (PMID 26959113, 2016). "Expression and activity of ILK, a serine/threonine kinase activated by integrin-mediated cell adhesion, is increased in several different cancer types." (PMID 26959113, 2016). "A recent study indicated that ILK/β-parvin/cofilin signaling pathways contributes to the initial formation of filopodium-like protrusions of carcinoma cells in EMT programming." (PMID 27096955, 2016). "Our data suggest that PARVA-overexpressing cancer cells promote tumour angiogenesis by stimulating the ILK–Akt–VEGF signalling pathway." (PMID 25738875, 2015). "The expression of integrin-linked kinase (ILK) has been reported to be involved in the regulation of integrin-mediated processes, including cancer cell proliferation, migration and invasion." (PMID 25760437, 2015). "While the PINCH1 expression data in human cancers are largely homogeneous, ILK expression seems to be more dependent on the tissue of origin, the grade of cellular differentiation and the tumor type." (PMID 26460618, 2015). "By acting as a core component of the regulatory loop, ILK promotes the aggressive and metastatic phenotype of cancer cells in a hypoxic setting through multiple oncogenic signaling pathways, including those mediated by Akt, GSK3β, and YB-1." (PMID 25821081, 2015).
cancer (continued). "Rictor also interacts with the integrin-linked kinase (ILK) to promote cancer cell survival through Akt Ser473 phosphorylation, and with PKCζ for cancer cell invasion and metastasis." (PMID 24086535, 2013). "Since ILK expression is frequently elevated in many cancer types, we investigated the effects of ILK overexpression on microtubule dynamics." (PMID 23349730, 2013). "In our previous work we have shown that conditional knockout of ILK in epithelial cells blunts the response to inflammation-induced cancer development in the colon." (PMID 24024606, 2013). "This is supported by a wealth of data regarding ILK’s role in various properties fundamental for cancer development such as proliferation, avoidance of apoptosis, angiogenesis and EMT." (PMID 24024606, 2013). "Several gene knockout studies have since revealed essential roles of ILK in embryonic development, tissue homeostasis, and organ function, while ILK levels have been shown to be elevated in many cancer types and correlates with poor prognosis." (PMID 23349730, 2013). "ILK levels have been found to be elevated in many cancer types and correlated to poor patient prognosis." (PMID 23825799, 2013). "Given that elevated ILK expression is common in many cancer types, we investigated effects of ILK overexpression on microtubule dynamics." (PMID 23349730, 2013). "Due to the significance of PKB/Akt pathway on tumorigenesis and the well established link between ILK and Akt in other cancers, the involvement of Akt in ILK-mediated functional effect was initiated." (PMID 21347395, 2011). "ILK overexpression and its dysregulated signaling cascades have been reported in many human cancers." (PMID 21347395, 2011). "ILK overexpression has been reported in many human cancers, with a positive correlation with cancer growth and an inverse correlation with survival." (PMID 20565980, 2010). "Numerous studies have provided a wealth of information on the crucial regulatory role for ILK as a protein kinase and also as a molecular scaffold and adaptor protein during cell spreading and migration in a variety of cancer cells." (PMID 20178627, 2010). "In vitro and in vivo work from others, however, indicate a prosurvival and tumor-promoting function of ILK, which suggested ILK as potent molecular cancer target." (PMID 19649326, 2009). "Widely anticipated to represent a very promising therapeutic target in several cancer indications, it is increasingly evident that optimal therapeutic benefits obtained using ILK targeting strategies will only be achieved in combination settings." (PMID 19409087, 2009). "Substantial preclinical evidence has indicated that inhibition of integrin linked-kinase (ILK) correlates with cytotoxic/cytostatic cellular effects, delayed tumor growth in animal models of cancer, and inhibition of angiogenesis." (PMID 19409087, 2009). "Stromal cells in cancer lesion were also positive to ILK, and rate of positive cells and intensity of the staining were not different from those of stromal cells in non-neoplastic lesion." (PMID 15631637, 2005). "In cancer cells, however, ILK activity is often increased, possibly as a result of a malfunctioning of upstream components in the integrin and growth factor signaling pathways." (PMID 15631637, 2005). "The possible mechanism behind the critical role of ILK in cancer progression could be due to its EMT-inducing effects with altered expression in epithelial markers, β-catenin and E-cadherin." (PMID 39525153, 2024). "The FAK/ILK/ERK/PI3K/NFB pathways are activated when FN1 binds to integrin, which causes overexpression of MMP-2 and MMP-9 and the destruction of the extracellular matrix (ECM) as well as the invasion of cancer cells." (PMID 37640804, 2023). "ILK also has multiple functions in different cancers, such as inducing EMT." (PMID 36900319, 2023). "ILK was overexpressed in many cancers and could regulate cell migration, metastasis and proliferation of cancer cells." (PMID 37568802, 2023).
cancer (continued). "Therefore, unclustering supernumerary centrosomes is an “Achilles Heel” of cancer cells and an important mechanism for anti-ILK chemotherapies." (PMID 37508338, 2023). "In cancer, ILK promotes EMT and enhances the migration and invasion of cancer cells." (PMID 36968277, 2023). "Bioinformatic analyses using IPA and ROMA software revealed significant up-regulation of multiple signaling pathways previously linked to cancer cells and their stromal microenvironment, including the three major MAPKs (ERK, JNK, p38), the PI3K/AKT/mTOR and integrin/ILK/actin cytoskeleton." (PMID 37696912, 2023). "Indeed, the engagement of CCDC25 by NET-associated DNA fostered the integrin-linked kinase (ILK) pathway leading to increased adhesion, motility, and growth of metastatic cancer cells in the liver." (PMID 37180120, 2023). "This suggests that ILK could have a role in the infiltration of different immune cells in the TME in a cancer context." (PMID 35692780, 2022). "However, ILK was lower expressed in cancer tissues and the prognosis will be worse when it was down-regulated." (PMID 35429970, 2022). "In addition to its role as part of the IPP, ILK promotes phosphorylation of key target proteins essential to processes critical for cancer progression, including survival, proliferation, migration, invasion, and EMT." (PMID 35804980, 2022). "Various studies reported the presence of ILK in the serum of cancer patients; however, further investigation is needed to assess whether it originates from exosomes present in serum or is free-floating secreted ILK." (PMID 35089438, 2022). "So we contend that ILK may be a relatively complex gene in cancer and need further studies in the future." (PMID 35429970, 2022). "This study testified that silencing long non-coding RNA cancer susceptibility candidate 9 could inhibit proliferation and invasion of CRC cells by miR-542-3p/integrin-linked kinase." (PMID 35427373, 2022). "The functional role of EV-derived TGFB1 and ILK in cancer has been reported earlier." (PMID 36505879, 2022). "Interestingly, ILK-mediated events were identified both in the stimulated normal epithelial cells and in the cancer cell-derived sEV." (PMID 35804980, 2022). "Therefore, different independent datasets exhibit contradictory results for ILK expression levels in cancers and normal tissues." (PMID 35692780, 2022). "We provide a new insight into the connection of ILK-senescence- inflammatory signaling pathway could be a new target for effective cancer therapy for GC." (PMID 35778385, 2022). "As many genotoxic chemotherapies are known to induce cellular senescence in normal cells, these studies suggest inhibition of ILK activity can be used as a more specific senescence inducer in cancer cells, as the survival and growth of these cancerous cells are addicted to activated ILK function." (PMID 35778385, 2022). "Much work on the therapeutic potential of genetic or pharmacological inhibition of ILK has been carried out, demonstrating significant downregulation of various oncogenic signaling pathways and thus suppression of tumor development and progression in several cancer types upon ILK’s “deactivation”." (PMID 35089438, 2022). "It has also been observed that LIM domain-containing protein 2 (LIMD2), a LIM-domain only protein specifically expressed in metastatic lesions, directly binds the kinase domain of ILK and increases ILK activity, leading to increased migration and invasion by cancer cells." (PMID 35804980, 2022). "This suggests that targeting ILK in KRAS mutant cancer cells might show less impact in sensitizing cancer cells to immune cell cytotoxicity." (PMID 35692780, 2022). "ILK has been revealed to contribute to different non-cancer diseases." (PMID 34163519, 2021). "Targeting integrin β4 (ITGB4) combined with ILK could increase the latent tumorigenic potential and decrease the invasive potential in cancer." (PMID 34966737, 2021).
cancer (continued). "Also, we analyze the possible role of ILK in the inflammatory response of senescence which is considered the deleterious factor in tumor progression and cancer immunity." (PMID 34163519, 2021). "Adaptor proteins and enzymes, such as FAK, Src, and integrin-linked kinase (ILK) lead to further downstream activation that modify the cytoskeleton, and promote migration, as a result many of these adaptor proteins are upregulated in cancer." (PMID 34439879, 2021). "The ILK/Akt/GSK3β axis has been reported to play roles in cancer cell growth and survival." (PMID 34591063, 2021). "The transcription factor Signal transducer and activator of transcription 3 (STAT3) may be regulated by ILK or Akt in inflammatory and cancer contexts." (PMID 34163519, 2021). "ILK interacts with different critical signaling pathways regulating important cellular processes that have an implication in inflammation and cancer." (PMID 34163519, 2021). "Moreover, eleven kinases were cancer-associated, some of which include FYN proto-oncogene tyrosine kinase (FYN), aurora kinase B (AURKB), and integrin-linked kinase (ILK)." (PMID 33499132, 2021). "The noticed upregulation of genes involved in the ILK and integrin signaling pathways in Catulin-GFP reporter cells emphasized previously published potential mechanism of action for catulin in cancer metastasis by activating the ILK-mediated Akt-NF-κB-αvβ3 signaling axis." (PMID 35008571, 2021). "Altogether, these data suggest that cancer cells develop functional invadopodia and perform subsequent invasion by establishing a compartmentalized, functional “signalsome” inside invadopodia, composed of β1-integrin, ILK, NHE1, p-ezrin and p-NHERF1." (PMID 33671549, 2021). "ILK is also involved in tumorigenesis and cancer progression." (PMID 34163519, 2021). "ILK also has been suggested to prevent senescence induction in the cancer context." (PMID 34163519, 2021). "We also examine how activating Toll-like receptors (TLRs) and their agonists in CRC could trigger immune responses against cancer, as a combination therapy with ILK inhibition." (PMID 34163519, 2021). "Again, ILK was found to be overexpressed in cancer tissues as compared to adjacent tissues." (PMID 31897228, 2020). "Among them, ILK was selected as key candidate based on the central signal transducing location in protein-protein interaction network and its key role in cancer progression and cancer cell motility." (PMID 31897228, 2020). "GO analysis of this group shows representation of biological pathways related to cell proliferation and motility, and genes that have been previously implicated in FP‐RMS pathogenesis (MAPK1, ILK, MCAM), as well as numerous other cancer‐promoting genes (based on literature survey)." (PMID 32697014, 2020). "Subsequently, we evaluated ILK expression levels between cancer and adjacent tissues." (PMID 31897228, 2020). "Interestingly, the ILK/Rictor complex formation was promoted more in cancer than in normal cells indicating a true involvement in cancer development." (PMID 33043811, 2020). "Furthermore, ILK has been validated to accelerate cancer cell invasion and migration by giving rise to EMT process." (PMID 30636169, 2019). "ILK is more established in the field and has been proposed as a potential anti-cancer therapeutic target being involved in tumor growth and invasion in many types of cancers while there was also a report of a suppressive effect seen on BC cells following ectopic expression of ILK." (PMID 30621163, 2019). "ILK-dependent Akt activation has been documented to participate in cancer metastasis." (PMID 26824419, 2016). "Likewise, HER2+-specific circRNAs (n = 245), annotated with over 1,500 protein-coding genes, had 855 cancer-related genes (p-value = 1.65E-14–2.24E-03) involved in Wnt signaling, Cdc42, and ILK signaling pathways." (PMID 27829232, 2016). "Besides that, ILK promotes the migration and invasion of cancer cells by facilitating the EMT process." (PMID 27034956, 2016).
cancer (continued). "There are, however, very few mechanistic in vivo studies on the role of ILK in cancer." (PMID 26349061, 2015). "A significant number of studies have identified that ILK is a potential oncogene and inhibition of ILK by siRNA or small molecules may be a potentially useful therapeutic approach for treating cancer." (PMID 25760437, 2015). "Moreover, promoter luciferase reporter assays revealed that HIF-1α facilitated transcriptional activation of ILK gene expression in a manner similar to that of hypoxia, confirming that HIF-1α regulates ILK gene expression in hypoxia-exposed cancer cells." (PMID 25821081, 2015). "These cancer cell lines are more sensitive to ILK inhibition than cells with two centrosomes." (PMID 24911651, 2014). "Indeed, ILK appears to be differentially required for growth and survival between normal and cancer cells." (PMID 23349730, 2013). "Such heterogeneous expression pattern of ILK in human cancers may suggest tissue or organ-specific functions of ILK." (PMID 21347395, 2011). "All these compelling evidences have demonstrated the oncogenic effect of ILK in cancer development." (PMID 21347395, 2011). "Expression of ILK was found to be elevated in many human cancers." (PMID 21347395, 2011). "Although strong evidence is presented that QLT0267 exerts these effects independent from ILK, further investigations are warranted to define the complete spectrum of this compound with regard to cancer target specificity and possible combinations with radiotherapy." (PMID 19649326, 2009). "Furthermore, siRNA mediated ILK silencing resulted in diminished cell spreading and actin cytoskeleton reorganization; results that help to explain ILK's role in the regulation of cancer cell motility and invasiveness." (PMID 19409087, 2009). "Targeted inhibition of ILK in cancer cells by various strategies can also lead to suppression of the AKT signaling pathway, inhibition of cell cycle progression, reduced vascular endothelial growth factor (VEGF) secretion in vitro, and reduced tumor growth in vivo." (PMID 19409087, 2009). "In the cancer cells of many patients, ILK expression was detected in both cytoplasm and nuclei." (PMID 15631637, 2005). "Inhibitors of ILK could emerge as targeted therapy drugs for cancer." (PMID 40171447, 2025). "In cancer cells, transcriptional coactivators, the Yes-associated protein (YAP) and its paralog TAZ (transcriptional coactivator with PDZ-binding motif) are translocated into the nucleus and activate the oncogenic cascades TGF-β/SMAD, WNT/β-Catenin and integrin-linked kinase (ILK)." (PMID 38672583, 2024). "Studies examining the therapeutic potential of ILK emphasized that targeting ILK could provide synergistic effects epically when used with the currently available chemotherapeutic agents in various types of cancer." (PMID 39525153, 2024). "Yet, not all cancer cells are susceptible to anti-ILK treatment alone." (PMID 37508338, 2023). "However, the role of ILK in cancer progression is yet to be fully understood." (PMID 38077324, 2023). "Since ILK correlation with the immune inhibitory molecules was greater in COAD, we decided to further investigate whether ILK is implicated in regulating PD-L1 (CD274) protein expression in CRC cell lines in vitro, our focused cancer model in this study." (PMID 35692780, 2022). "Therefore, it is hypothesized that ILK may have a facilitative effect on the viability of cancer cells, which in turn makes them insensitive to anticancer drugs." (PMID 35477364, 2022). "We believe that ILK is a potential marker for the detection and identification of pre-metastatic cancers and, therefore, could be exploited as an anti-metastasic target in these cancers." (PMID 33671549, 2021). "Therefore, ILK may have an impact on SASP secretions in the cancer context, possibly by regulating NF-κB." (PMID 34163519, 2021). "ILK may play a role in cellular senescence in different contexts including aging and cancer." (PMID 34163519, 2021).